OR1L4 (olfactory receptor family 1 subfamily L member 4)
Description:
Odorant receptor.
Synonyms: OR9-E; OR1L5; OR9-29; OST046
Tractability: Antibody: UniProt places it where antibodies can reach, with medium confidence; UniProt predicts a signal peptide or a membrane-spanning region; its Gene Ontology location is reachable by antibodies, with medium confidence.
Gene: Protein-coding gene on chromosome 9 (122,723,990 to 122,724,925, forward strand). Ensembl gene ENSG00000136939.
Subcellular location: Cell membrane
Pathways (Reactome):
Sensory Perception: Expression and translocation of olfactory receptors
Gene Ontology:
Molecular function: olfactory receptor activity; G protein-coupled receptor activity; signaling receptor activity
Biological process: signal transduction; detection of chemical stimulus involved in sensory perception of smell; G protein-coupled receptor signaling pathway; sensory perception of chemical stimulus
Cellular component: plasma membrane; membrane
Genetic constraint (gnomAD): Loss-of-function variants: 8 observed, 8.71 expected, observed/expected ratio (o/e) 0.92, 90% interval 0.54 to 1.62. That is too few expected variants to judge how well the gene tolerates losing a copy. Missense variants: 291 observed, 363.08 expected, observed/expected ratio (o/e) 0.8, 90% interval 0.73 to 0.88. Synonymous variants: 123 observed, 142.21 expected, observed/expected ratio (o/e) 0.86, 90% interval 0.75 to 1.
Homologues: Orthologues: chimpanzee OR1L4 (96% identical), dog OR1L6 (87% identical). Paralogues in human: OR1L6 (94% identical), OR1L1 (68% identical), OR1L3 (65% identical), OR1L8 (61% identical), OR1F1 (55% identical), OR7C1 (55% identical), OR1N1 (54% identical), OR1K1 (53% identical), OR1N2 (53% identical), OR7C2 (53% identical), OR7D4 (53% identical), OR7D2 (53% identical), and 116 more.
Diseases named in the same sentence as OR1L4 in open-access papers:
OR1L4 is named in the same sentence as 2 diseases in open-access papers, as found by Europe PMC text mining. Sharing a sentence is not in itself a finding about the gene and the disease. The quoted sentences say what the papers report.
embryonal carcinoma (1 paper, 2022). A non-seminomatous malignant germ cell tumor characterized by the presence of large germ cells with abundant cytoplasm resembling epithelial cells, geographic necrosis, high mitotic activity, and pseudoglandular and pseudopapillary structures formation. "Mutations in ADAMTS20, ARHGAP10, OR1L4, PDS5A, and RPLP0 were only found in mixed germ cell tumors, while mutations in B3GNT8, CAPN7, FAT4, GRK1, TACC2 and TRAM1L1 were only observed in embryonal carcinoma, and their mutation frequency was around 2%." (PMID 36713456, 2022).
OR1L4 also shares sentences with these, for which no sentence is quoted: mixed germ cell tumor (1 paper).